KRAS (KRas proto-oncogene, GTPase)
Diseases named in the same sentence as KRAS in open-access papers (continued):
Sharing a sentence is not in itself a finding about the gene and the disease.
cancer (continued). "The novel KRAS mutant E31D, which also harbored a conserved amino acid substitution, was predicted to be benign in all in silico prediction platforms used, but showed highly oncogenic properties in all cancer hallmarks tested." (PMID 32365913, 2020). "From this perspective, the assessment of KRAS prenylation rates may provide important information on the progression of KRAS-driven cancers." (PMID 32887255, 2020). "Previous studies demonstrating a constitutive fragmented mitochondrial morphology in oncogenic KRAS or BRAF driven cancers prompted us to seek whether such endogenously activating mutations in colorectal cancerous cell lines have any role in tumorigenesis." (PMID 33738242, 2020). "In inducible Atg7-knockout mice, the growth of KRAS-driven lung tumors was significantly inhibited before any signs of neurotoxicity, indicating that therapeutic window for autophagy inhibition exists in some cancers." (PMID 32641008, 2020). "ARS853 was efficacious in KRAS G12C mutant cancer cells through the trapping mechanism, and ongoing phase I/II trials (NCT03785249 and NCT04330664) are assessing the efficacy of MRTX849, a small molecule that selectively modifies the mutant cysteine residue in KRAS G12C." (PMID 33008426, 2020). "One of the most common drivers in human cancer is the mutant KRAS protein." (PMID 31988705, 2020). "Here, we summarise the current knowledge of KRAS-induced immune-modulatory effects in cancer." (PMID 33116132, 2020). "Brequinar treatment in KRAS mutant cancer cells was reversed by uridine treatment." (PMID 32824193, 2020). "In addition to these cancers, drivers of pancreatic cancers and thyroid cancers have been shown to exhibit KRAS (G12C, G12D) and BRAF (V599E) among MAPK pathways." (PMID 32260561, 2020). "Additionally, using fries and EWAK* within the osprey suite, we designed the tightest known binder of KRas, a heavily studied cancer target that interacts with a number of different proteins." (PMID 32511232, 2020). "We have shown that PAWI-2 could reverse cancer stemness and overcome drug resistance in an integrin β3 KRAS-dependent hPCSCs (i.e., FGβ3 cells)." (PMID 32514015, 2020). "We speculated that this may have resulted from the anchorage dependence of sustained KRAS expression in cancer cells." (PMID 33052229, 2020). "ddPCR unraveled high MAFs of KRAS in all PDOs, further validating our cultures as cancer organoids." (PMID 32492856, 2020). "PDAC, the cancer with the highest incidence of KRAS mutations, however, does not present with very high TMB27." (PMID 32194994, 2020). "Preclinical and preliminary clinical data suggest that cancers with KRAS mutant may be sensitive to MEK or ERK inhibitors." (PMID 32083805, 2020). "This is also due to the fact that KRAS mutant cancer lacks effective therapeutic interventions." (PMID 32170113, 2020). "Low plasma adiponectin levels were found to be associated with KRAS-mutant CRC risk but not with KRAS wild-type cancer risk." (PMID 33167521, 2020). "Cancer cells may adopt various strategies, such as amplified KIT signaling, increased EGFR phosphorylation, KRAS mutations oncogene, or increased NRG1 for activating HER2/3 kinases to survive crizotinib treatments." (PMID 32164629, 2020). "While these previously undescribed findings have potential therapeutic significance in identifying a path to suppress KRAS-driven cancer self-renewal, it would be helpful to determine whether pharmacological inhibition of ICMT can achieve the same effect." (PMID 32561852, 2020).
cancer (continued). "The impact on KRAS function through the inhibition of its modification by ICMT results in decreased RAF–MEK activation and subsequent decrease in TAZ protein, leading to the loss of self-renewal ability/stemness in KRAS-driven cancer cells." (PMID 32561852, 2020). "Thus, overall these results support the role of HO-1 in regulating KRAS-mutant cancer cell sensitivity to vitamin C." (PMID 32393788, 2020). "Despite the limited number of clinical studies investigating drugs targeting inflammation and immunomodulatory effects specifically in KRAS-mutant cancers, the forthcoming results from the trials in cancers often driven by KRAS mutations will be provide crucial knowledge for future studies." (PMID 33116132, 2020). "As we have shown that KRAS causes NLRP3/IL-1β activation, targeting this axis may also be promising to achieve a therapeutic synergism with other anti-cancer therapies." (PMID 33116132, 2020). "Moreover, we found KRAS shorten the CSS in patients with cancers occurred at left colon (HR = 1.28 (95% CI [1.15–1.42]), p < 0.05) and rectum (HR = 1.23 (95% CI [1.07–1.43]), p < 0.05) but not right colon (HR = 1.07 (95% CI [0.97–1.19]), p > 0.05)." (PMID 32547859, 2020). "Genetic aberrations such as KRAS mutations are specific to cancer and do not exist in normal tissues." (PMID 32903495, 2020). "Discovering an essential and predictable epigenetic response to mutant KRAS expression either within one cancer type, across multiple cancer types, or specificity to a particular KRAS mutation (i.e. G12D), could reveal other potential anti-cancer targets." (PMID 32576853, 2020). "In summary, targeting KRAS-induced effects on the immune system in cancer either solely or in combination with immunotherapies has great potential to increased clinical response in cancer patients." (PMID 33116132, 2020). "KRAS is a powerful oncogene responsible for the development of many cancers." (PMID 32887255, 2020). "Analysis of 523 cancer-relevant genes and of immune cells infiltration in primary and metastatic tissues revealed atypical genomic trajectories (TMB decrease, KRAS and SMAD4 regressive mutations), specific genetic events (ERBB2 point mutations) and scarce T-cell infiltration." (PMID 32332709, 2020). "Importantly, the Ras gene enriched in rare codons used in our screen models more closely the rare codon-enriched sequence of human KRAS, which is the most frequently mutated RAS family member in human cancers." (PMID 33296356, 2020). "As described in the Section entitled “Computational redesign of the c-Raf-RBD:KRas protein-protein interface,” KRas is an important cancer target that has been heavily studied and exhibits a thoroughly optimized protein-protein interface in its interactions with its effectors." (PMID 32511232, 2020). "KRAS is the predominant mutated gene in MOC and may be related to the progression from benign to malignant tumors." (PMID 32556513, 2020). "In KRAS-mutant cancer cells with or without LKB1 loss, increased expression of SSP genes and high serine synthesis allow the cells to tolerate serine starvation for survival." (PMID 33511116, 2020). "We hypothesized that a drug may exhibit KRAS-dependent cytotoxicity in cancer cells if this drug could reverse the KRAS-driven gene signature." (PMID 32947833, 2020).
cancer (continued). "Although the discovery of conventional ICB has revolutionized the therapy of several cancers, unfortunately PDAC, the cancer with the highest incidence of KRAS mutations, does not form part of this group." (PMID 32194994, 2020). "We transfected cancer cells carrying KRAS-Q61K (H460) mutant with either control or PTPN2 siRNA." (PMID 33122197, 2020). "We investigated whether the fasting/FMD potentiates the anti-cancer effect of vitamin C against different KRAS-mutant cancer models." (PMID 32393788, 2020). "However, these CRC cells also contain mutations in other cancer related genes (HCT116: KRAS, PIK3CA, CTNNB1, BRCA2, CDKN2A etc.; SW480 or SW620: KRAS and APC etc.), which constitute a unique pathological context in every CRC cell." (PMID 32388500, 2020). "In addition to ITPR2, EGFR is frequently mutated or overexpressed in various cancer types, and in PDAC particularly, EGFR is essential for KRAS-driven pancreatic carcinogenesis." (PMID 32629766, 2020). "Exploring the KRAS-mediated methylation changes in these pathways may be a deserving direction toward identifying supplementary strategies to target KRAS-driven cancers." (PMID 32576853, 2020). "Interestingly, cancers expressing oncogenic KRAS manage to escape antitumor immunity via upregulation of programmed cell death 1 ligand 1 (PD-L1)." (PMID 32194994, 2020). "While it was reported that KRAS mutant cancer cells are highly sensitive to PLK1 inhibitors, detailed mechanisms underlying the sensitivity are largely unknown." (PMID 32486290, 2020). "Among five cases of KRAS discordance, three showed KRAS mutations in cancer gene panel testing but not in KRAS mutation analysis." (PMID 31999789, 2020). "The observed downregulation of E‐cadherin and upregulation of EMT markers may further support the KRAS enrichment which is a popular event in aggressive cancer types." (PMID 32979859, 2020). "To test the hypothesis that SLIT2 could inhibit macropinocytosis in cancer cells, we chose two KRAS-transformed adenocarcinoma cell lines, PANC-1 and DLD-1." (PMID 32807784, 2020). "Furthermore, we found that treatment with vitamin C significantly upregulated HO-1, while FMD/STS reversed this effect both in vitro and in vivo in KRAS-mutant cancer cells." (PMID 32393788, 2020). "We confirm that high cholesterol in the PM helps KRas-4B mutant stay in its constitutively active state, which suggests that high cholesterol intake can increase mortality and may promote cancer progression for cancer patients." (PMID 33266473, 2020). "Moreover, some cancer cells (e.g. derived from breast tumours or melanomas or KRAS‐driven cancer cell lines) have shown CQ‐mediated cell growth inhibition that was independent of autophagy." (PMID 32715647, 2020). "Interestingly, we observed that KRAS, an oncogene that plays a key role in the development and progression of various carcinomas, was downregulated in iBET-151-treated cells." (PMID 33412753, 2020). "The remaining 13 of 27 cases showed a homogeneous distribution of KRAS amplified carcinoma cells." (PMID 32571252, 2020). "In order to test whether REDD1 loss induced these changes in human cells we ablated REDD1 via lentiviral shRNA in KRAS mutant A549 carcinoma cells." (PMID 32273287, 2020).
cancer (continued). "Furthermore, while BRAF inhibitors are effective in blocking growth of cancer cells driven by the BRAF-V600E mutation, BRAF inhibition paradoxically activates MAPK signaling in KRAS mutant tumors through inducing increased dimerization of BRAF with RAS." (PMID 31681559, 2019). "Collectively, these features make KRAS one of the most attractive targets in cancer biology." (PMID 31413817, 2019). "Meanwhile, it was also reported that TBX19 acts downstream of KRAS in human cancer." (PMID 31223310, 2019). "Together, these data highlight that KRAS-mutant cancers hijack diverse processes to evolve." (PMID 31519898, 2019). "Indeed, this is related to the more general question of why only mutant KRAS is oncogenic, and, to date, this remains one of the most challenging questions in cancer biology." (PMID 31635338, 2019). "The absence of contamination by cancer cells in the CAF cultures was verified by the lack of ubiquitous tumoural KRAS mutations." (PMID 30575030, 2019). "The use of KRAS mutation as a biomarker of exclusion for patients receiving anti-EGFR therapy, specifically cetuximab and panitumumab was a significant landmark in the advancement of cancer therapy." (PMID 31565185, 2019). "Two additional discrepancies (blood positive for KRAS mutation and cancer samples negative for KRAS mutation) were noted in two cases (patients 4 and 11)." (PMID 30368666, 2019). "Targeting KRAS-interacting SNAREs with a SNAP23-degrading protease thus also impairs tumorigenesis, further indicating that targeting SNARE proteins may represent a alternative therapeutic opportunity in KRAS-driven cancer." (PMID 31712554, 2019). "In vivo tumorigenesis experiments with 15 cancer cell lines in a variety of genetic backgrounds revealed striking sensitivity of tumors driven by oncogenic KRAS, but not other Ras isoforms, to loss of these vesicular transport proteins." (PMID 31712554, 2019). "The comparison of KRAS mutation status between EBC–DNA and cancer tissue was performed in 19 cases." (PMID 30368666, 2019). "It will now be of great interest to further evaluate whether ADAM17‐mediated sIL‐6R shedding and ERK activation are restricted to mutant KRAS LAC or are also a driver event in other mutant KRAS cancers (e.g., colorectal and pancreatic)." (PMID 30833304, 2019). "Our in silico analysis showed that down-regulation of miR-15b-5p, miR-30e-3p and miR-374b-5p in SCI individuals may have KRAS as one of the targets gene presents in the three most frequent types of cancer related to SCI." (PMID 31444279, 2019). "Several other regulators showing differential activation pattern among DD and LS genes are involved in cell proliferation and cancer, e.g., KRAS [z-score = 2.14, -log(p-value) = 3.15] predicted to be activated in DD, or FOXM1 inhibited in LS [z-score = -3.24, -log(p-value) = 2.98]." (PMID 31249595, 2019). "Moreover, the effects of those inhibitors on downstream signalling in cancer cell lines harbouring BRAF, KRAS, or EGFR mutations were evaluated to assess the relationship between dimerization and paradoxical activation." (PMID 30679688, 2019). "Thus, understanding how HFD and oncogenic KRAS alter the redox status and cellular glutathione levels should provide new insights into the design of redox-based cancer therapeutics." (PMID 30819189, 2019). "KRAS has been confirmed as a proto-oncogene which induces tumorigenesis in several cancers." (PMID 30917791, 2019). "Despite the emergence of SHP2 inhibitors for the treatment of cancers harbouring mutant KRAS, the mechanism underlying SHP2 activation of KRAS signaling remains unclear." (PMID 30644389, 2019). "Therefore, the quest for alternative and effective treatment options for patients harboring mutant KRAS tumors should also focus on the crosstalk between mutant KRAS cancer cells and the surrounding TME." (PMID 31847096, 2019).
cancer (continued). "Concomitant treatment with MAPK and autophagy inhibitors might therefore represent a novel strategy to target KRAS-driven cancers." (PMID 31544066, 2019). "These are representative known cancer predisposition genes: BRCA1, BRCA2, KRAS and RET." (PMID 31391007, 2019). "Interestingly, in the last few years, CRC has been classified in consensus molecular subtypes (CMS): CMS1 (microsatellite instable tumors), CMS2 (chromosomal instable tumors), CMS3 (KRAS mutated tumors), and CMS4 (cancer with mesenchymal characteristics)." (PMID 31238520, 2019). "Thus, manipulation of the opposing functions of KRAS in cell proliferation/survival versus cell death should be an attractive approach to develop new strategies for the treatment of various types of cancers, especially those with mutant KRAS." (PMID 30971271, 2019). "Furthermore, the KRAS protein and DNA vaccines have emerged as a novel immunotherapeutic strategy to tackle oncogenic KRAS-addicted cancers in preclinical models or as adjuvant treatment options in clinical settings." (PMID 31438559, 2019). "Over 90% of low-grade PanIN-1 lesions have already acquired a KRAS mutation, but obviously most do not progress to invasive cancer." (PMID 30611220, 2019). "Similarly, functionally inhibiting ORP5 and ORP8 by inhibiting PI4KIIIα-mediated synthesis of phosphatidyl-4-phosphate at the PM selectively inhibited the growth of KRAS-dependent cancer cell lines over normal cells." (PMID 31451509, 2019). "Furthermore, to compare KRAS mutations in DNA extracted from pre-surgery EBC, blood samples and cancer tissue in 19 NSCLC patients were collected." (PMID 30368666, 2019). "We here show for the first time that deletion of IQGAP1 dramatically induces MEK nuclear translocation in KRAS mutant cancer cells, and that mutant KRAS could restrain MEK/β-TrCP in the cytoplasm via IQGAP1, then downregulating YAP expression." (PMID 30833665, 2019). "KRAS has the highest mutation rate compared to HRAS and NRAS in various types of cancers." (PMID 30971271, 2019). "Oncogenic KRAS signaling proceeded by different downstream effectors may lead to phenotypic variance in cancer, but to what extent the downstream effectors contribute to the oncogenic phenotype is not fully understood." (PMID 31612108, 2019). "KRAS, is an oncogene in multiple cancer types, including menaloma." (PMID 30779739, 2019). "KLF3 could inhibit cellular growth and suppress transformation mediated by oncogenic KRAS (V-Ki-ras2 Kirsten rat sarcoma viral oncogene homologue) and increase apoptosis in cancer cells (Fernandez-zapico, Lomberk & Tsuji, 2011)." (PMID 31293827, 2019). "Specific mutations in KRAS lock the protein into the GTP-bound state resulting in constitutive signaling which gives mutated cells a growth advantage and leads to development of cancer." (PMID 31399087, 2019). "Because KRAS-activating mutations cluster around the nucleotide-binding pocket, these mutations cause RAS to be persistently GTP-bound and constitutively active, resulting in the hyperactivation of signaling networks to drive cancer growth and progression." (PMID 31681587, 2019). "Importantly, the batch effect causes substantial differences in germline variant distribution patterns across numerous genes, including prominent cancer predisposition genes such as BRCA1, RET, MAX, and KRAS." (PMID 31391007, 2019). "This leads to constitutive activation of KRAS and upregulation of downstream signaling cascades that promote many of the hallmarks of cancer, including sustained proliferation, metabolic reprogramming, resistance to apoptosis, immunological escape, cell migration, and metastasis." (PMID 31413817, 2019). "The KRAS gene is one of the first human oncogenes studied in cancer." (PMID 31217933, 2019).